INS (insulin)
Diseases named in the same sentence as INS in open-access papers (continued):
Sharing a sentence is not in itself a finding about the gene and the disease.
diabetes (continued). "Diabetes itself accelerates the aging process and affects muscle metabolism through multiple mechanisms such as insulin resistance and oxidative stress, making elderly diabetic patients more prone to sarcopenia." (PMID 40873790, 2025). "Changes in glycemic and metabolic parameters in individuals with type 1 diabetes mellitus (T1DM) following initiation of insulin degludec/aspart (IDegAsp)." (PMID 41293743, 2025). "Insufficient insulin production or resistance to its effects results in diabetes mellitus, a chronic metabolic disorder characterized by high blood glucose levels." (PMID 39930590, 2025). "Contemporary research indicates that the suppression of proteasomal activity can indirectly attenuate the biosynthesis of insulin and thus influence the onset of diabetes." (PMID 40092641, 2025). "Cycling, resistance training, and combined aerobic and resistance exercises have been shown to effectively enhance fasting blood glucose levels, insulin secretion, and insulin sensitivity in individuals with diabetes." (PMID 40951419, 2025). "The SLC7 family of transporters plays a critical and multifaceted role in metabolic processes that are highly relevant to diabetes, primarily through mechanisms linking amino acid sensing, insulin signaling, and pancreatic β-cell function." (PMID 40469683, 2025). "Our preliminary post-pump workshop survey showed that providers were more inclined to prescribe insulin pump technologies at an earlier duration of diabetes diagnosis." (PMID 40110444, 2025). "Diabetes is characterized by chronic hyperglycemia resulting from insufficient insulin secretion, insulin action defects, or their combination." (PMID 41312353, 2025). "Diabetes mellitus, a fast-growing chronic metabolic disease, is characterised by insufficient insulin production by the pancreas or the body's inability to use insulin action." (PMID 39931095, 2025). "On the nineteenth hospital day, the patient was discharged on basal insulin and oral diabetes medications, with plans for outpatient follow-up." (PMID 40859516, 2025). "In recent years, advancements in diabetes technology have introduced the era of closed-loop systems, offering the promise of enhanced glycaemic control through the automation of insulin delivery." (PMID 39792171, 2025). "Diabetes is a chronic metabolic disease characterized by either insufficient insulin production or impaired insulin uptake." (PMID 39399837, 2025). "In particular, how to effectively restore key nodes in the insulin signaling pathway to prevent or reverse the progression of diabetes continues to be a significant research focus." (PMID 39948335, 2025). "Firstly, clinical trials with controlled randomizations are needed, with endpoints that include: assessing glucose homeostasis, insulin sensitivity, and a decrease in the development of diabetes-related complications." (PMID 40843204, 2025). "Diabetes mellitus is a group of metabolic disorders defined by hyperglycemia resulting from defects in insulin secretion, insulin action, or both." (PMID 41368573, 2025). "Obesity is the primary factor contributing to diabetes in both industrialized and developing nations; the alteration in dietary patterns cannot surpass the significance of obesity in creating an insulin-resistant condition." (PMID 40141412, 2025). "The finding of our study that DEPS-R scores were significantly lower in the CSII group within the poor glycemic control group (HbA1c > 9%) suggests a potential protective effect of insulin pump therapy against diabetes-specific disordered eating." (PMID 41010976, 2025). "When comparing the two groups, the DigiDiaS care group had a shorter duration of diabetes, more use of insulin pumps than insulin pens for insulin delivery, and a lower well-being score compared with the usual care group." (PMID 40846321, 2025).
diabetes (continued). "IAPP oligomers play a crucial role in the pathogenesis of diabetes mellitus, particularly in the destruction of pancreatic beta cells and the dysfunction of insulin production." (PMID 39859479, 2025). "Materials and Methods: This review synthesizes data from studies on MBS and EBT outcomes, focusing on predictors for diabetes remission such as preoperative insulin use, diabetes duration, HbA1c, and C-peptide levels." (PMID 40005466, 2025). "XA affects the production and release of insulin by binding to it, influencing the development of diabetes." (PMID 40137174, 2025). "According to the World Health Organization (WHO), diabetes mellitus is a chronic condition resulting from either insufficient insulin production or the body’s inability to utilize insulin effectively." (PMID 41155632, 2025). "Diabetes is a chronic metabolic disease characterized by hyperglycemia, which results from defects in insulin secretion, insulin action, or both." (PMID 39841995, 2025). "Further mediation analysis highlights diabetes and smoking as significant mediators of insulin’s effect on OA, with diabetes and smoking respectively accounting for 74.26%, 70.11%, and 43.34% of the mediation effect through various indicators." (PMID 41398760, 2025). "Propensity score matching was used to match for age, gender, race, ethnicity, BMI, essential hypertension, type of diabetes, long term insulin use, coronary artery disease, hypercholesterolemia, and baseline DR severity." (PMID 40348919, 2025). "Diabetes is a chronic disease that occurs from either insufficient insulin production by the pancreas or ineffective insulin action by the body." (PMID 40766758, 2025). "Future research will focus on enhancing cell survival, glucose responsiveness, and long-term integration, aiming to create a reliable and scalable source of insulin-producing cells for diabetes treatment." (PMID 40124184, 2025). "Both the American Diabetes Association (ADA) and the Brazilian Society of Diabetes (SBD) guidelines recommends initiation of insulin when the glycated hemoglobulin (HbA1c) levels exceed 10 and 9% respectively, despite other treatments." (PMID 39810242, 2025). "Particular emphasis was placed on linking microbiota composition and functional shifts with metabolic outcomes, including glycemic control, insulin resistance, lipid regulation, and diabetes-related complications." (PMID 41200610, 2025). "Diabetes is a complex trait influenced by numerous genes, with variations in genes related to insulin production and secretion, ion channel function, and glucose metabolism being central to disease development." (PMID 40149950, 2025). "Diabetes management requires a multifaceted approach, including lifestyle modification, medication, and insulin therapy." (PMID 40549787, 2025). "Mice with β-cell-specific Tfb1m deletion (Tfb1mβ−/−) develop progressive insulin secretory failure and overt diabetes." (PMID 41369350, 2025). "Intensive insulin treatment can help delay the onset of diabetes-related complications, and many patients with type 2 diabetes require insulin therapy at some stage to achieve or maintain good glycemic control." (PMID 40242444, 2025). "We next assessed the function of microRNA-450a-5p-inhibitor in the regulation of glucose homeostasis and insulin sensitivity in diabetes (db/db) mice." (PMID 39912972, 2025). "From a sleep disorder perspective, OSA increases insulin resistance, which makes diabetes control more difficult." (PMID 41158621, 2025). "The successful experiment led to sustained insulin independence and restoration of glycemic control, opening up new possibilities for treating diabetes." (PMID 40574081, 2025). "The level of adherence to insulin therapy seen in this study was 67.20%, which is seen as suboptimal given the high and growing burden of diabetes in Ghana alongside the growing use of insulin." (PMID 39854487, 2025).
diabetes (continued). "One study reported a reduction of greater than 25% in insulin requirements and fewer diabetes-related complications with diabetes-specific formulas compared to standard formulas." (PMID 39940355, 2025). "This evidence suggests that the amounts of carbohydrates, protein, and fat and their insulin secretion ability should be considered in the personalised dietary treatment of diabetes." (PMID 40566351, 2025). "A greater benefit from MRA therapy was observed in patients with diabetes, particularly those treated with insulin, in a sub‐analysis of the EMPHASIS‐HF trial." (PMID 40955522, 2025). "The data clearly indicate that while most diabetics are insulin resistant, a significant number also have evidence of decreased insulin production and relative insulin deficiency." (PMID 40284198, 2025). "They play a crucial role in glucose homeostasis and the pathogenesis of diabetes by regulating insulin secretion mechanisms." (PMID 40162315, 2025). "Management of hyperglycemia in hospitalized patients usually requires insulin therapy, especially in those with pre-existing diabetes, and a close monitoring of glucose levels is essential." (PMID 40893589, 2025). "TPDEs significantly improved diabetes‐induced alterations in serum insulin levels, antioxidant status, and pancreas‐related gene expression." (PMID 40887321, 2025). "Bromelain has been suggested as a useful insulin-independent therapeutic molecule for the control and management of type 2 diabetes mellitus." (PMID 40864762, 2025). "In the T1DEXI cohort, 44% of participants were using HCL systems, 41% were on standard insulin pumps and 15% were managing diabetes via MDI." (PMID 41059660, 2025). "SCFAs have been shown to enhance insulin sensitivity by alleviating gut inflammation, a factor known to contribute to insulin resistance and the development of diabetes." (PMID 40149935, 2025). "Both groups received three biweekly teleconsultations with Diabetes Nurse Educators for insulin dose adjustments, followed by two clinic visits at three-month intervals." (PMID 41476921, 2025). "Our findings indicate that experimental diabetes increased gluconeogenesis, as evidenced by the elevated activities of glucose-6-phosphatase and fructose-1,6-bisphosphatase, likely due to decreased insulin levels in diabetic rats." (PMID 40283884, 2025). "Due to her history of early‐onset diabetes, the possibility of maturity‐onset diabetes of the young (MODY) was considered; however, her insulin secretion was adequate, and insulin resistance was consistent with type 2 diabetes mellitus." (PMID 41321883, 2025). "Diabetes and glucose intolerance are highly prevalent in cirrhosis of any etiology, due to the effect of cirrhosis on insulin‐induced glucose uptake (insulin resistance) and pancreatic beta cell insulin secretion." (PMID 40664615, 2025). "Diabetes is a serious, chronic illness that arises when the pancreas fails to produce enough insulin or when the body is unable to effectively use the insulin it produces." (PMID 39883698, 2025). "During diabetes mellitus, since there is low insulin or insulin resistance, the glucose in the blood stream will not be absorbed." (PMID 40424230, 2025). "Diabetes mellitus, a collection of endocrine and metabolic disorders marked by hyperglycemia due to insulin secretion defects or insulin resistance, affects a significant portion of the global population." (PMID 40406527, 2025). "While some countries advance toward comprehensive diabetes management, others still struggle with basic access to life-preserving insulin." (PMID 40864470, 2025). "KLF11 regulates glucose metabolism and insulin, with variations affecting pain sensitivity and diabetes." (PMID 40313396, 2025). "In terms of organisation, all elective participants in our study had their diabetes and insulin treatment acknowledged before surgery, with plans for prioritisation on theatre lists, aligning with national recommendations." (PMID 41358572, 2025).
diabetes (continued). "The transition from insulin resistance to overt diabetes occurs when β-cells fail to maintain adequate compensatory insulin secretion." (PMID 41426805, 2025). "Another chronic disease is type 2 diabetes mellitus (T2DM) that is a multifactorial condition primarily marked by decreased insulin sensitivity, defects in insulin secretion, and chronic inflammation." (PMID 40665105, 2025). "The phenomenon of clinical inertia, particularly in the context of insulin treatment intensification, has been observed in various settings, including tertiary public diabetes centers with limited pharmacologic options." (PMID 40909026, 2025). "It is more common in diabetes mellitus type 1, but it can also occur in insulin-treated type 2 diabetes." (PMID 41007688, 2025). "Two patients developed brittle diabetes requiring continuous glucose monitoring and frequent insulin titration." (PMID 41450393, 2025). "The associations identified between high diabetes distress and younger age, current use of insulin, and a history of diabetes foot ulcer are in line with previous studies." (PMID 39972441, 2025). "As is well known, insufficient understanding of the role and status of insulin in the treatment of diabetes is universal." (PMID 40242444, 2025). "Recursive Feature Elimination (RFE) was used to choose features (eg. contagious glucose, BMI & insulin) to get the most influence on diabetes prediction, for the Predict Diabetes from Medical Records dataset." (PMID 40391337, 2025). "Particularly in individuals with diabetes, the decline in muscle strength and muscle mass is pronounced due to insufficient insulin secretion and action." (PMID 41228530, 2025). "Out of the nine patients with clinically relevant postoperative complications and concomitant diabetes, six (66%) patients were insulin dependent." (PMID 40307470, 2025). "An observational study in Japanese type 2 diabetes patients indicated that improved HbA1c levels during oral diabetes medication or insulin therapy correlated with increased walk pace." (PMID 40119457, 2025). "The majority managed their diabetes through oral medication 253 (65.9%), with a smaller percentage on insulin therapy or a combination of oral and insulin treatment." (PMID 40066153, 2025). "Type 1 diabetes mellitus is a chronic disease resulting from the autoimmune destruction of pancreatic insulin-producing cells, typically manifesting during adolescence." (PMID 40650152, 2025). "Diabetes mellitus is an etiologically heterogeneous chronic disorder of glucose metabolism characterized by elevated plasma glucose levels due to impaired insulin secretion, insulin resistance, or a combination of both." (PMID 41202067, 2025). "•In diabetes, insulin use is a primary contributor to transcriptome variability and promotes vascular inflammation." (PMID 41377472, 2025). "For many years, insulin for diabetes treatment was derived from animal pancreas because of its structural and functional similarity to human insulin." (PMID 40574081, 2025). "Our study substantiates a reduction in the level of m6A modification in people with diabetes following intensive insulin therapy." (PMID 40299682, 2025). "Overall, disruptions in both oxidative phosphorylation and fatty acid metabolism significantly influence the pathophysiology of diabetes, leading to energy deficits, insulin resistance, and metabolic complications." (PMID 41203872, 2025). "Diabetes mellitus is a chronic metabolic disorder marked by hyperglycemia due to impaired insulin secretion, insulin action, or both." (PMID 40724606, 2025). "In our study, patients who were undergoing pharmacological treatment of diabetes, especially with oral agents and insulin, were found to express far more symptoms of SFN and nerve pain." (PMID 41035812, 2025). "MicroCore PTH addresses osteoporosis with teriparatide delivery, while JewelPUMP offers another insulin delivery option for diabetes." (PMID 39433696, 2025).
diabetes (continued). "Diabetes mellitus (DM) is a chronic metabolic disorder resulting from abnormalities in insulin secretion, insulin action, or both." (PMID 40429855, 2025). "Nanotechnology has enabled the continual development of better glucose monitoring and insulin delivery procedures, considerably increasing the quality of life for people with diabetes." (PMID 40574088, 2025). "FGF1 functions as a key metabolic regulator that governs glucose homeostasis and insulin sensitivity, and has shown therapeutic potential for type 2 diabetes mellitus." (PMID 41430037, 2025). "Diabetes mellitus is a chronic metabolic disease demarcated by elevated blood glucose levels due to impaired insulin secretion, insulin action, and at times both." (PMID 40806100, 2025). "The majority were using insulin throughout the COVID-19 era and experienced changes to their in their non-insulin diabetes medications." (PMID 41008502, 2025). "Of interest in this study is the fact that the patient was a product of maternal diabetes treated with insulin, while our previous study was carried out in a patient who was a product of a normal gestation." (PMID 40004100, 2025). "Type 2 diabetes mellitus (T2D) arises from the interplay between peripheral insulin resistance and pancreatic β‐cell dysfunction, ultimately leading to impaired glucose utilization and chronic hyperglycemia." (PMID 41208560, 2025). "It increases the insulin sensitivity and improves the insulin signaling pathways and finally it attenuates diabetes/stress-induced hyperglycemia." (PMID 40656624, 2025). "In the DKA group, 57.7% (41/71) were established diabetics and the most common type of insulin used was glargine U‐100a (53.7%, 22/41), followed by human recombinant protamine zinc insuline (17.1%, 7/41)." (PMID 40880442, 2025). "In 2 prospective trials, clamp-measured insulin sensitivity was stratified according to diabetes duration and glycemic control at 2 weeks, 3 to 6 months, and 9 months to 1 year after diagnosis." (PMID 39998445, 2025). "According to information provided by the deceased’s relatives, her past medical history included diabetes mellitus, arterial hypertension, and knee osteoarthritis, for which she was receiving insulin, irbesartan, and hydrochlorothiazide." (PMID 40718305, 2025). "Acceptance of diabetes as a part of the identity was highlighted by CHF8’s parents with the anecdote of their daughter wearing an insulin pump and that “it has been years that she has been wearing it, so it is like part of her in the end." (PMID 40565407, 2025). "Individuals with diabetes, particularly those using insulin, face substantial challenges when fasting during the Islamic month of Ramadan due to prolonged periods without food or drink and an increased risk of hypoglycemia." (PMID 41510436, 2025). "Diabetes-type composition varied: in GV-high, type 1 diabetes represented 34%, type 2 on oral drugs 28%, and type 2 on insulin 38%; in GV-low, the respective proportions were 14%, 55% and 31% (χ2 = 8.7, p = 0.013)." (PMID 41156463, 2025). "Most participants reported feeling confident as they read the information or comments from the internet and comments on social media from other expectant mothers who had diabetes during pregnancy and required insulin injections." (PMID 39951457, 2025). "Comorbidities included diabetes mellitus in three patients, all of whom achieved effective perioperative glycemic control with insulin." (PMID 40606974, 2025). "Diabetes mellitus is a chronic disease, characterized by insufficient insulin production by the pancreatic β-cells as well as by insulin resistance." (PMID 39859258, 2025). "This study investigates the potential role of microplastics in the development of diabetes mellitus and assesses their presence in individuals undergoing insulin therapy." (PMID 41304478, 2025).